SLC22A12 (solute carrier family 22 member 12)
Description:
Electroneutral antiporter that translocates urate across the apical membrane of proximal tubular cells in exchange for monovalent organic or inorganic anions. Involved in renal reabsorption of urate and helps maintaining blood levels of uric acid. Mediates urate uptake by an exchange with organic anions such as (S)-lactate and nicotinate, and inorganic anion Cl(-). Other inorganic anions such as Br(-), I(-) and NO3(-) may also act as counteranions that exchange for urate. Also mediates orotate tubular uptake coupled with nicotinate efflux and to a lesser extent with lactate efflux, therefore displaying a potential role in orotate renal reabsorption. Orotate transport is Cl(-)-dependent.
Synonyms: RST; URAT1; OAT4L; hURAT1; UAT
Tractability: Small molecule: an approved drug acts on it; a structure with a bound ligand is known; a high-quality ligand is known; it belongs to a druggable protein family. Antibody: UniProt places it where antibodies can reach, with high confidence; its Gene Ontology location is reachable by antibodies, with high confidence; UniProt predicts a signal peptide or a membrane-spanning region. PROTAC: a small molecule that binds it is known.
Target class: SLC superfamily of solute carriers; Electrochemical transporter; SLC22 family of organic cation and anion transporters; Transporter
Safety:
Unwanted effects reported when the protein is acted on. In parentheses: how it was acted on, where the effect was seen, and who reports it.
fever (source: ClinPGx)
Gene: Protein-coding gene on chromosome 11 (64,590,641 to 64,602,353, forward strand). Ensembl gene ENSG00000197891.
Subcellular location: Apical cell membrane
Pathways (Reactome):
Disease: Defective SLC22A12 causes renal hypouricemia 1 (RHUC1)
Transport of small molecules: Organic anion transport by SLC22 transporters
Gene Ontology:
Molecular function: PDZ domain binding; protein binding; urate transmembrane transporter activity; transmembrane transporter activity
Biological process: response to xenobiotic stimulus; urate metabolic process; urate transport; cellular homeostasis; transmembrane transport; cellular response to insulin stimulus; renal urate salt excretion
Cellular component: apical plasma membrane; extracellular exosome; membrane; plasma membrane; brush border membrane
Genetic constraint (gnomAD): Loss-of-function variants: 54 observed, 48.02 expected, observed/expected ratio (o/e) 1.12, 90% interval 0.9 to 1.41. The upper end of that interval is the gene's LOEUF score, 1.41, which puts it in group 5 of 6, group 1 being the genes least tolerant of losing a copy. Missense variants: 672 observed, 718.12 expected, observed/expected ratio (o/e) 0.94, 90% interval 0.88 to 1. Synonymous variants: 334 observed, 317.92 expected, observed/expected ratio (o/e) 1.05, 90% interval 0.96 to 1.15.
Homologues: Orthologues: chimpanzee SLC22A12 (99% identical), dog SLC22A12 (83% identical), pig SLC22A12 (83% identical), rat Slc22a12 (74% identical), mouse Slc22a12 (74% identical), guinea pig SLC22A12 (72% identical), macaque SLC22A12 (63% identical), zebrafish oatx (41% identical), zebrafish si:dkey-166k12.1 (33% identical), zebrafish slc22a4 (30% identical), Caenorhabditis elegans oct-1 (28% identical), Drosophila melanogaster Orct2 (28% identical), and 44 more. Paralogues in human: SLC22A11 (52% identical), SLC22A10 (48% identical), SLC22A24 (46% identical), SLC22A25 (45% identical), SLC22A6 (44% identical), SLC22A9 (44% identical), SLC22A8 (41% identical), SLC22A7 (35% identical), SLC22A13 (31% identical), SLC22A3 (30% identical), SLC22A5 (29% identical), SLC22A1 (28% identical), and 10 more.
Diseases named in the same sentence as SLC22A12 in open-access papers:
SLC22A12 is named in the same sentence as 81 diseases in open-access papers, as found by Europe PMC text mining. Sharing a sentence is not in itself a finding about the gene and the disease. The quoted sentences say what the papers report.
hyperuricemia (175 papers, 2012 to 2026). An abnormally high level of uric acid. "This study is the first to demonstrate that the CC genotype of SLC22A12 (rs559946) reduces the risk of higher SUA in Chinese Tibetan patients with hyperuricemia." (PMID 41137353, 2025). "Variants in SLC22A12 have been linked to altered urate handling, contributing to hyperuricemia and increasing the risk of gout." (PMID 39409183, 2024). "An in vitro study revealed that mice previously treated with reverastrol had reduced renal SLC22A12 expression and, consequently, hyperuricemia caused by uric acid reabsorption by URAT1 in the kidney." (PMID 35505381, 2022). "The uric acid reabsorption transporter URAT1 encoded by the hyperuricemia-related gene SLC22A12 reabsorbs urate from filtered urine." (PMID 35807846, 2022). "Mutations in the SLC22A12 gene are associated with diseases with abnormal serum uric acid levels, including hypouricemia, hyperuricemia, gout, and nephrolithiasis." (PMID 34249694, 2021). "Intriguingly, we found homozygous Trp258* mutations in SLC22A12 gene causing RHUC1 while concurrent mutations reported to be associated with hyperuricemia were also discovered including ABCG2 (Gln141Lys) and SLC17A1 (Thr269Ile)." (PMID 32375679, 2020). "We found a case of RHUC1 carrying mutations in SLC22A12 gene accompanied with compensatory mutations associated with hyperuricemia, representing the first report showing coexistence of the mutations with opposed potential to regulate urate concentrations." (PMID 32375679, 2020). "The aims of our study were to identify which variants of the SLC2A9 and SLC22A12 genes existed in a cohort of 250 individuals with primary hyperuricemia and gout, and at what frequency they existed." (PMID 32759716, 2020). "We looked at genetic variants of genes encoding the major reabsorption proteins GLUT9 (SLC2A9) and URAT1 (SLC22A12) and their association with hyperuricemia and gout." (PMID 32759716, 2020). "On the other hand, SLC22A12 rs11231825 has been shown to be associated with reduced renal urate excretion and hyperuricemia in German and Han Chinese populations." (PMID 30621105, 2019). "For instance, the SNV rs121907892 of SLC22A12 was significantly associated with the prevalence of hyperuricemia and serum concentration of uric acid in all the genetic models (P < 2.0 × 10− 16)." (PMID 29124443, 2018). "This protein is encoded by the SLC22A12 gene, which is a genetic risk factor for inducing hyperuricemia." (PMID 28623927, 2017). "Follow-up replications across multiple ethnics including New Zealand populations, Japanese and Han Chinese successively identified additional SNPs in SLC22A12 gene associated with gout or hyperuricemia." (PMID 26290326, 2015). "However, further stratified analyses showed that SLC22A12 rs559946 was negatively associated with SUA levels in hyperuricemia patients, and the CC genotype reduced their risk of higher SUA levels." (PMID 41137353, 2025). "Interestingly, we are the first to find that the SLC22A12 rs559946 C allele may protect Tibetan hyperuricemia patients from higher SUA levels." (PMID 41137353, 2025). "Therefore, the aim of this study was to genotype the polymorphisms of the genesABCG2 (Q191K),SLC22A12 (517G>A), andXDH (518T>C) in 860 young Mexican volunteers aged between 18 and 25 years of age as predisposing factors of hyperuricemia associated with risk factors of cardiovascular disease." (PMID 34631016, 2021). "GWAS studies of hyperuricemia have identified key susceptibility loci involved in uric acid transport and purine metabolism: Primary transporters include GLUT9 (SLC2A9) and URAT1 (SLC22A12), which mediate uric acid reabsorption." (PMID 41601955, 2026). "Association between SLC2A9, SLC22A12 and SLC22A11 polymorphisms and the risk of higher SUA values in hyperuricemia group." (PMID 41137353, 2025). "Hyperuricemia has a strong genetic component (40%–70%): related genes include SNPs in SLC22A12, ABCG2, HNF1A, and HNF4A." (PMID 41195208, 2025).
hyperuricemia (continued). "In this case-control study, we investigated for the first time the association between rs1014290 (SLC2A9), rs559946 (SLC22A12), and rs1783811 (SLC22A11) with SUA levels and hyperuricemia in a Tibetan population." (PMID 41137353, 2025). "Another significant gene associated with hyperuricemia and clinical gout is SLC22A12, which encodes the transporter protein urate transporter-1 (URAT1)." (PMID 40093021, 2025). "Since hyperuricemia is the key known factor that leads to gout, many of the consistently top-associated genes, such as SLC2A9, SLC22A12, or ABCG2, are involved in urate transport." (PMID 41155224, 2025). "Among hyperuricemia patients, SLC22A12 (rs559946) was negatively correlated with SUA levels after adjusting for gender and age." (PMID 41137353, 2025). "A total of 194 Tibetan patients with hyperuricemia and 304 healthy Tibetan controls were enrolled, and polymorphisms in SLC2A9 (rs1014290), SLC22A12 (rs559946), and SLC22A11 (rs1783811) were identified using high-resolution melting." (PMID 41137353, 2025). "A SLC22A12 inhibitor verinurad are in phase II clinical trials for the treatment of hyperuricemia and chronic kidney disease." (PMID 39850557, 2024). "Another SLC22A12 inhibitor dotinurad has been approved in some Asian countries for the treatment of hyperuricemia and gout." (PMID 39850557, 2024). "The increased expression of ALPK1 and SLC22A12 in the blood of patients with gout could be associated with their altered metabolic status, which favors a long-term chronic condition with recurrent acute episodes if hyperuricemia and comorbidities are maintained." (PMID 35505381, 2022). "SLC22A12 produces a genetic variation that contributes to urate absorption and is a key factor in hyperuricaemia and gout." (PMID 34335246, 2021). "Many urate transporter genes, such as SLC22A12/URAT1 and SLC2A9/GLUT9, whose dysfunctional variants cause renal hypouricemia are also reported to have an association with gout and hyperuricemia." (PMID 33517564, 2021). "A larger cohort would provide a clearer view of the effects of the variants of the SLC22A12 and SLC2A9 genes on the development of hyperuricemia and gout." (PMID 32759716, 2020). "In a cohort of 250 individuals with primary hyperuricemia and gout, we used direct sequencing to examine the SLC22A12 and SLC2A9 genes." (PMID 32759716, 2020). "The SNPs rs55975541 in CDC42BPG, and rs11231825/rs9734313 in SLC22A12/NRXN2, and rs10897526 in MAP4K2 on chromosome 4 were previously reported to be associated with hyperuricemia or gout." (PMID 29558500, 2018). "Given the heterogeneity evident in risk conferred for hyperuricemia at SLC2A9 and SLC22A12 in different populations studied so far, further investigation of these genes is warranted." (PMID 25268603, 2014). "Previously, we and others examined the SNPs SLC22A12 and SLC2A9, and their associations with gout or hyperuricemia in different Chinese populations." (PMID 24857923, 2014). "In the genetic analysis, we tested whether the expression quantitative trait locus (eQTL) that influences the expression of SLC22A12, as well as its LOF mutation, modifies the association between hyperinsulinemia and hyperuricemia." (PMID 40100301, 2025). "Research has identified various single nucleotide polymorphisms (SNPs) in the SLC2A9 and SLC22A12 gene that are associated with an increased risk of hyperuricaemia and gout, such as G/A genotype for rs3733591 in the SLC2A9 gene and a C/C genotype for rs893006 in the SLC22A12 gene." (PMID 40093021, 2025). "In summary, we demonstrated the mechanism by which hyperinsulinemia acts through URAT1 to increase serum urate levels and that the gene-environment interaction involving SLC22A12 influences the positive association between hyperinsulinemia and hyperuricemia." (PMID 40100301, 2025).
hyperuricemia (continued). "And the rs559946 (SLC22A12) deserves more attention from researchers with interest in this field to provide more theoretical basis for targeting interventions at this locus for the treatment of hyperuricemia." (PMID 41137353, 2025). "Associations between SLC2A9, SLC22A12 and SLC22A11 SNPs and hyperuricemia." (PMID 41137353, 2025). "Urate-lowering drugs are agents used to treat hyperuricaemia, capable of modulating the activity of key enzymes responsible for the metabolism and excretion of urates such as xanthine oxidoreductase (XO), urate transporter 1 [URAT1/SLC22A12] e glucose transporter 9 (GLUT9)." (PMID 36556930, 2022). "The genetics of hyperuricemia, which is universally accepted to be the cause of gout, involves genes such as SLC2A9 (encodes for GLUT9), SLC22A12 (encodes for URAT1), SLC22A13 (encodes for OAT4) and ABCG2; these are mostly involved in uric acid reabsorption and secretion." (PMID 35456363, 2022). "Indeed, urate transporter genes such as SLC22A12 (also known as URAT1), SLC2A9 (GLUT9), and ABCG2 (BCRP) have been markedly associated with SUA, hyperuricemia, and gout." (PMID 30993211, 2019). "As a target for drugs that treat hyperuricemia, the expression level of SLC22A12 could be an important determinant of drug response." (PMID 26856248, 2017). "In particular, miRNAs could regulate the expression of urate transporter genes, e.g., miR-34a regulates the mRNA of the solute carrier family 22 member 12 (SLC22A12) gene to ultimately repress the uric acid transporter 1 (URAT1) expression in the animal model of hyperuricemia." (PMID 37426193, 2023). "The development of hyperuricemia has been shown to be associated with multiple genetic factors and the uric acid transporter protein genes SLC2A9 (encoding GLUT9), SLC22A12 (encoding URAT1), SLC17A1 (encoding NPT1) and ABCG2 were most strongly correlated with changes in serum uric acid levels." (PMID 35909538, 2022). "Despite the low gene expression of SLC22A12 in our study, it could be related to hyperuricemia and the consequent kidney damage in people with a longer time with the disease and poor control of hyperuricemia." (PMID 35505381, 2022). "Overall, the SLC family, particularly SLC22A12 and SLC2A9 along with ABCG2, play important roles in UA transportation, and their dysfunction can contribute to hyperuricemia and gout." (PMID 38674582, 2024). "We detected five allelic variants in SLC22A12 (URAT1) transporter, but all these variants are synonymous in protein sequence, so we supposed that these variants are no protective effect for hyperuricemia or gout." (PMID 38222853, 2024). "None of the variants of the known gout and hyperuricemia-related genes were co-segregated with the disease phenotype in this family, including ABCG2, SLC2A9, SLC22A11, SLC22A12, SLC17A1, SLC17A3, PDZK1, and INHBB." (PMID 39433541, 2024). "Thus, besides the classic target XO that plays a critical role in uric acid production, transporters, such as organic anion transporter 1 (OAT1, SLC22A6) and urate transporter 1 (URAT1, SLC22A12) in kidney, might be promising targets for treating hyperuricemia." (PMID 31511824, 2019).
gout (106 papers, 2011 to 2026). A condition characterized by painful swelling of the joints, which is caused by deposition of urate crystals. "Associations between variations in SLC22A12 and clinical gout have been demonstrated across diverse populations." (PMID 40093021, 2025). "Specifically, the rs121907892 and p.W258X in the SLC22A12 gene significantly reduces the risk of gout." (PMID 39850557, 2024). "In contrast, the rs475688 variant (C/C genotype) and the p.N82N synonymous mutation in SLC22A12 are positively associated with an increased risk of gout." (PMID 39850557, 2024). "We identified male-specific SNP-trait associations of gout in the SLC22A12 region, specifically an upstream variant rs2360872." (PMID 36635277, 2023). "The alpha kinase 1 variant in combination with the ABCG2 SNP (rs2231142), the SLC2A9 SNP (rs1014290), or the SLC22A12 SNP (rs475688 and rs3825016) is linked to gout in the recessive model." (PMID 35813212, 2022). "Meta-analysis showed that SLC22A12 rs3825016 and rs3825018 are risk factors for gout and HUA, while rs475688 is a protective factor for HUA." (PMID 35922835, 2022). "Associations of metabolic syndrome and obesity with variants of SLC22A12 (rs11602903 and rs11231825), which predispose patients to gout, have been reported." (PMID 35505381, 2022). "The lack of nonsynonymous variants of SLC22A12 in our cohort was not so surprising since it is likely that these variants act as gout suppressors based on the reabsorption function of the URAT1 protein." (PMID 32759716, 2020). "Major transporters involved in renal urate disposition that are encoded by gout-risk genes include SLC22A12 (encoding URAT1), SLC2A9 (encoding Glut9), and the urate secretory transporter ABCG2 (ATP-binding cassette)." (PMID 33330529, 2020). "Our study aimed to assess the relationship between polymorphisms in ABCG2 and SLC22A12 and gout susceptibility in Vietnamese." (PMID 30621105, 2019). "Further investigation should be implemented to obtain more information on the association of ABCG2 and SLC22A12 SNPs or other different genetic variants with gout." (PMID 30621105, 2019). "Three SNPs, rs780094 in GCKR, rs1183201 in 17A1 and rs505802 in SLC22A12 were significantly associated with gout in our samples." (PMID 26290326, 2015). "Three SNPs, rs780094 in GCKR, rs1183201 in SLC17A1 and rs505802 in SLC22A12 were confirmed to be significantly associated with gout and SUA concentrations." (PMID 26290326, 2015). "Using European descent Czech populations, we performed a study of SLC2A9 and SLC22A12 genes previously identified as being associated with serum uric acid concentrations and gout." (PMID 25268603, 2014). "Rare variants in the SLC22A12 locus have been associated with SU and gout in African-Americans and gout in Japanese and Micronesians." (PMID 24360580, 2013). "This is, to our knowledge, the first report of nominally significant association of SLC22A12 with gout in European Caucasians." (PMID 24360580, 2013). "The European Caucasian sample set revealed nominally significant (P <0.05) associations with gout at two block-3 SNPs: rs475688 and rs7932775 (SLC22A12; OR = 1.26, P = 0.043; OR = 1.32, P = 0.033, respectively)." (PMID 24360580, 2013). "Our data therefore suggest that multiple common variants within the SLC22A12 locus contribute to the risk of gout, in a population-dependent manner." (PMID 24360580, 2013). "The aim of this study was to test genetic variation across the SLC22A11/SLC22A12 locus for association with risk of gout in NZ sample sets." (PMID 24360580, 2013). "In addition to HLA-B*58:01, ongoing research is illuminating how common variants in genes encoding urate transporters – such as ABCG2, SLC2A9 (GLUT9), SLC22A12 (URAT1), and others – modulate serum urate levels and gout risk in different populations." (PMID 41329531, 2025).